MIDN (midnolin)
Description:
Facilitates the ubiquitin-independent proteasomal degradation of stimulus-induced transcription factors such as FOSB, EGR1, NR4A1, and IRF4 to the proteasome for degradation. Promotes also the degradation of other substrates such as CBX4 (By similarity). Plays a role in inhibiting the activity of glucokinase GCK and both glucose-induced and basal insulin secretion.
Synonyms: Stx
Tractability: PROTAC: ubiquitination databases record sites on it.
Gene: Protein-coding gene on chromosome 19 (1,248,331 to 1,259,145, forward strand). Ensembl gene ENSG00000167470.
Subcellular location: Nucleus, nucleolus; Nucleus; Cytoplasm, cytosol
Subcellular location (Human Protein Atlas): Nucleoplasm
Gene Ontology:
Molecular function: molecular adaptor activity; protein binding; kinase binding
Biological process: proteasomal ubiquitin-independent protein catabolic process; negative regulation of glucokinase activity; negative regulation of insulin secretion
Cellular component: cytoplasm; nucleus; cytosol; nucleolus
Genetic constraint (gnomAD): Loss-of-function variants: 21 observed, 29.03 expected, observed/expected ratio (o/e) 0.72, 90% interval 0.51 to 1.04. The synonymous counts are far from expectation, so gnomAD's model fits this gene poorly and the ratio says little. Missense variants: 760 observed, 596.52 expected, observed/expected ratio (o/e) 1.27, 90% interval 1.2 to 1.35. Synonymous variants: 403 observed, 267.56 expected, observed/expected ratio (o/e) 1.51, 90% interval 1.39 to 1.64.
Homologues: Orthologues: macaque MIDN (99% identical), mouse Midn (93% identical), rat Midn (92% identical), chimpanzee MIDN (92% identical), pig MIDN (91% identical), guinea pig MIDN (79% identical), dog MIDN (76% identical), zebrafish midn (60% identical), tropical clawed frog midn (56% identical), Drosophila melanogaster stx (35% identical).
Diseases named in the same sentence as MIDN in open-access papers:
MIDN is named in the same sentence as 41 diseases in open-access papers, as found by Europe PMC text mining. Sharing a sentence is not in itself a finding about the gene and the disease. The quoted sentences say what the papers report.
Parkinson disease (7 papers, 2017 to 2025). A progressive degenerative disorder of the central nervous system characterized by loss of dopamine producing neurons in the substantia nigra and the presence of Lewy bodies in the substantia nigra and locus coeruleus. "Knocking out MIDN in cells increased the expression of parkin, which is considered as a major causative gene in Parkinson's disease." (PMID 40111059, 2025). "MIDN, which regulates parkin expression, has been associated with Parkinson's Disease by regulating neurite outgrowth and Parkin expression in neuronal cells." (PMID 37405477, 2023). "MIDN promotes the expressing of parking E3 ubiquitin ligase, and MIDN loss can trigger Parkinson’s disease." (PMID 35913967, 2022). "Midnolin has previously been reported to potentially regulate neurogenesis-related genes and pancreatic beta cell glucokinase activity, and possibly be associated with Parkinson’s disease though the data are controversial." (PMID 35326575, 2022). "Subsequent studies indicated that midnolin regulated neurite outgrowth and was strongly correlated with Parkinson’s disease because of lower MIDN gene copy numbers." (PMID 40002690, 2025). "MIDN was identified as a biomarker for Parkinson's disease by regulating parkin." (PMID 40111059, 2025). "10.5% of patients with sporadic Parkinson's disease lacked one copy of MIDN in genome." (PMID 40111059, 2025).
liver cancer (5 papers, 2022 to 2025). An epithelial or non-epithelial malignant neoplasm that arises from the liver. "Together, these data supported that MIDN promotes progression in liver cancer and its function was associated with β‐Catenin." (PMID 40111059, 2025). "To further explore the function of MIDN in liver cancer, we used the TCGA‐LIHC dataset to identify mutations of key proteins that are closely related." (PMID 40111059, 2025). "To investigate the cellular functions of MIDN, we employed a liver cancer cell line (Huh‐7) to investigate the role of MIDN." (PMID 40111059, 2025). "In liver cancer, the MIDN/CTNNB1/MMP9 axis promotes progression through inducing a suppressive tumour immune microenvironment." (PMID 40111059, 2025). "NR4A1, PSMC1, and EGR1 were selected as MIDN-interacted proteins, and these four molecules were co-expressed in pancreatic cancer, liver cancer, urothelial cancer, melanoma, and breast cancer." (PMID 40002690, 2025). "Compared with other cancers, we found that the transcriptional expression of MIDN in liver cancer is consistent with the protein level, and its transcriptional level is significantly correlated with prognosis and immune cell infiltration." (PMID 40111059, 2025). "Analysis of the Depmap database showed that MIDN was highly detected in liver cancer as well as peripheral nervous system cancer, whereas it was lowly expressed in vulva/vagina cancer, eye cancer, and so on." (PMID 40002690, 2025). "Kweon's another study revealed that MIDN promotes liver cancer progression through retinoic and lipid metabolism." (PMID 40111059, 2025). "The tumour sizes and growth rates of Huh‐7 tumours in nude mice were dramatically reduced after the expression of MIDN was knocked down, indicating that MIDN contributes to the progression of liver cancer." (PMID 40111059, 2025). "They found that knocking down MIDN in liver cancer cells inhibited the growth through retinoic acid metabolism or lipid metabolism." (PMID 40111059, 2025). "The MIDN/CTNNB1/MMP9 axis promotes liver cancer progression via inducing a suppressive tumour immune microenvironment." (PMID 40111059, 2025). "Recently, MIDN has also been reported to promote proliferation and tumor formation in liver cancer cells, and the severity of nonalcoholic fatty liver disease is attenuated in heterozygous Midn knockout (KO) mice." (PMID 39264361, 2024). "To this end, we recently discovered that expression of the gene midnolin promotes liver cancer and correlates with poor prognosis in liver cancer patients." (PMID 35326575, 2022). "The correlation of MIDN and CTNNB1 suggested that MIDN might be an important regulator in liver cancer." (PMID 40111059, 2025). "Kweon's work demonstrated that MIDN was an oncogene in liver cancer." (PMID 40111059, 2025). "Similarly, MIDN was particularly highly expressed in monocytes/macrophages (Mono/Macro) according to the liver cancer dataset (GSE140228)." (PMID 40111059, 2025). "Therefore, to elaborate the functional role of MIDN in liver cancer, the protein expression level and, especially, the nuclear expression of MIDN need to be analyzed." (PMID 40002690, 2025). "MIDN is a potential prognostic biomarker in liver cancer and bladder cancer." (PMID 40111059, 2025). "MIDN knockdown inhibited liver cancer cell growth and colony formation, which could be rescued by exogenous expression of MIDN." (PMID 38084259, 2023). "To investigate the role of midnolin in liver cancer cells, we generated clones of Hepa1-6 cells with stable knockdown of midnolin (sh1 to sh5) versus stable expression of scramble (scr) control, via lentivirus transduction followed by selection of single cells by limiting dilution." (PMID 35326575, 2022). "Importantly, a study reported that blocking MIDN suppressed the proliferation, colony formation, and tumor growth of liver cancer cells and mechanically disrupted retinoic acid and lipid metabolisms, indicating that MIDN exhibited oncogenic roles in liver cancer." (PMID 40002690, 2025).
liver cancer (continued). "Hence, we concluded that suppression of midnolin reduces the tumorigenicity of liver cancer cells." (PMID 35326575, 2022). "Targeting midnolin may be useful in future therapy for liver cancer." (PMID 35326575, 2022). "Based on the Human Protein Atlas (HPA) database, we found that MIDN, NR4A1, PSMC1, and EGR1 were all positively expressed in liver cancer, pancreatic cancer, urothelial cancer, breast cancer, and melanoma." (PMID 40002690, 2025). "MIDN interacted with NR4A1, EGR1, and PSMC1, and it was especially co-expressed in liver cancer, pancreatic cancer, urothelial cancer, breast cancer and melanoma." (PMID 40002690, 2025). "Similarly, our data found that MIDN could be a negative biomarker for liver cancer, and it might promote the progression through β‐catenin." (PMID 40111059, 2025).
hepatocellular carcinoma (2 papers, 2023 to 2025). A malignant tumor that arises from hepatocytes. "Midnolin (MIDN) was highly expressed in hepatocellular carcinoma (HCC) tumors compared with normal liver." (PMID 38084259, 2023). "Another study found that overexpressed midnolin facilitated the progression of hepatocellular carcinoma (HCC), also discovering that the suppression of midnolin disrupted retinoic acid/lipid metabolism in HCC cells and restrained tumor growth." (PMID 40002690, 2025).
multiple myeloma (2 papers, 2023 to 2024). "IRF4, another midnolin substrate, is a lineage-specific transcription factor that is essential for the function and homeostasis of mature B and T cells and is an oncogenic driver of multiple myeloma." (PMID 37616343, 2023). "Based upon the finding that MIDN promoted proteasome-mediated degradation of IRF4, and reports that IRF4 promoted c-Myc expression necessary for myeloma cell survival, we analyzed IRF4 and c-MYC levels in MidnKD/KD splenic B cells by immunoblot." (PMID 38625151, 2024).
acute myeloid leukemia (1 paper, 2025). Acute myeloid leukemia (AML) is a group of neoplasms arising from precursor cells committed to the myeloid cell-line differentiation. "The high expression level of MIDN was correlated with unfavorable overall survival (OS) in patients with LGG and acute myeloid leukemia (LAML), with poor disease-specific survival (DSS) in patients of LGG and LUSC, and with a shortened progression-free interval (PFI) in LUSC patients." (PMID 40002690, 2025).
Autoimmunity (1 paper, 2022). The occurrence of an immune reaction against the organism's own cells or tissues. "IFIT3, MIDN, and ILR1 belong to pathways associated with interferon regulation or autoimmunity and were identified in the immune response subclusters (C3 and C4.2)." (PMID 35494238, 2022).
breast carcinoma (1 paper, 2025). "In summary, our findings indicated that MIDN was overexpressed in many cancers such as gastric cancer and breast cancer, and under-expressed in a lot of cancers, such as COAD." (PMID 40002690, 2025). "Results showed that the knockdown of MIDN suppressed the colony formation of breast cancer cells and upregulated the demethylase FTO both in breast and gastric cancer cells." (PMID 40002690, 2025). "Significantly, our study revealed that MIDN was highly expressed in gastric and breast cancers, and the knockdown of MIDN upregulated FTO protein levels both in SNU-216 and MCF-7 cells." (PMID 40002690, 2025). "The knockdown of MIDN suppressed the colony formation of breast cancer cells and upregulated FTO both in breast and gastric cancer." (PMID 40002690, 2025). "Furthermore, in breast cancer cells, the downregulation of MIDN suppressed the colony formation abilities and lessened cell-cycle-associated and stemness-associated genes; in gastric cancer, the knockdown of MIDN diminished the mRNA levels of Nanog and LDHA." (PMID 40002690, 2025).
cervical squamous cell carcinoma (1 paper, 2025). A squamous cell carcinoma arising from the cervical epithelium. "In the GEPIA2 database, high MIDN expression was linked with shortened disease-free survival (DFS) in patients with uveal melanoma (UVM) and cervical squamous cell carcinoma and endocervical adenocarcinoma (CESC), as well as with prolonged DFS in patients of esophageal carcinoma (ESCA)." (PMID 40002690, 2025).
cholangiocarcinoma (1 paper, 2025). A carcinoma that arises from the intrahepatic biliary tree (intrahepatic cholangiocarcinoma) or from the junction, or adjacent to the junction, of the right and left hepatic ducts (hilar cholangiocarcinoma). "Our study uniquely identifies MIDN’s overexpression in rare cancers, such as cholangiocarcinoma, and highlights its prognostic value across diverse cancer types, providing novel insights into its potential as a therapeutic target." (PMID 40002690, 2025).
esophageal adenocarcinoma (1 paper, 2025). A malignant tumor with glandular differentiation arising predominantly from Barrett mucosa in the lower third of the esophagus. "In the Kaplan–Meier Plotter database, MIDN expression was also negatively associated with the OS and relapse-free survival (RFS) in esophageal squamous cell carcinoma (ESCC) and esophageal adenocarcinoma (EAC)." (PMID 40002690, 2025).
esophageal cancer (1 paper, 2025). A primary or metastatic malignant neoplasm involving the esophagus. "Both the GEPIA2 and Kaplan–Meier Plotter databases revealed that high expression of MIDN was associated with favorable outcome of esophageal cancer patients, indicative of the robustness of results across different databases." (PMID 40002690, 2025).
gastric cancer (1 paper, 2025). A primary or metastatic malignant neoplasm involving the stomach. "Fourth, our findings revealed the oncogenic roles of MIDN in breast and gastric cancers; however, its roles in other types of cancers still need to be investigated." (PMID 40002690, 2025). "Immunofluorescence, qRT-PCR, and Western blotting assays were used to evaluate the biological roles of MIDN in breast and gastric cancer cells." (PMID 40002690, 2025). "Our study further examined the biological functions of MIDN in breast and gastric cancers in which MIDN was overexpressed." (PMID 40002690, 2025). "Our results indicated that the knockdown of MIDN downregulated AIFM2 in gastric cancer." (PMID 40002690, 2025). "Strikingly, silence of MIDN upregulated FTO protein expression in both breast and gastric cancer cells." (PMID 40002690, 2025).
liver disease (1 paper, 2022). "We have previously observed, in novel p300 S89A knock-in mice that displayed enhanced Wnt/CBP/beta-catenin signaling, that major metabolic defects existed and midnolin was one of the most significantly differentially expressed genes in livers, pointing to a role for midnolin in liver disease." (PMID 35326575, 2022).
lymphoma (1 paper, 2024). A malignant (clonal) proliferation of B- lymphocytes or T- lymphocytes which involves the lymph nodes, bone marrow and/or extranodal sites. "The sensitivity of Eμ-Myc transgenic B cells to loss of MIDN likely results from the known dependence of Myc-driven lymphoma on the UPR for survival in the context of upregulated protein synthesis." (PMID 38625151, 2024).
maturity onset diabetes (1 paper, 2025). "KEGG enrichment analysis indicated that MIDN-interacted proteins were associated with maturity onset diabetes in young patients and the Epstein–Barr virus infection." (PMID 40002690, 2025).
neuroblastoma (1 paper, 2024). Neuroblastoma (NB) is the most common solid, extracranial childhood tumor. "In addition, the co-immunoprecipitation of MIDN-Flag with EGR1 was also detected in SH-SY5Y cells, a human neuroblastoma cell line, when treated with insulin (1 μM, 2 h)." (PMID 39264361, 2024).
nonalcoholic fatty liver disease (1 paper, 2025). "With the help of an MIDN knocked‐out mouse model, Kweon's study illustrated that MIDN attenuated the severity of nonalcoholic fatty liver disease by reducing cholesterol and lipid metabolism." (PMID 40111059, 2025).
ovarian serous cystadenocarcinoma (1 paper, 2025). A malignant serous cystic epithelial neoplasm arising from the ovary. "For example, MIDN expression was found to be positively linked with all m6A-, m5C-, and m1A-associated molecules in ovarian serous cystadenocarcinoma (OV)." (PMID 40002690, 2025). "The MIDN mRNA level was markedly linked with stages of COAD, KIRP, ovarian serous cystadenocarcinoma (OV), and UCEC (p < 0.05)." (PMID 40002690, 2025).
pheochromocytoma and paraganglioma (1 paper, 2025). "The MIDN level was positively linked with the stemness in THYM, pheochromocytoma and paraganglioma (PCPG), THCA, and so on, and negatively associated with the stemness in rectum adenocarcinoma (READ), LIHC, and so on." (PMID 40002690, 2025).
prostate adenocarcinoma (1 paper, 2025). "MIDN expression was significantly correlated with the infiltration of CD8+ T cell, CD4+ T cell, B cell, macrophage, neutrophil, and DC both in prostate adenocarcinoma and liver hepatocellular carcinoma." (PMID 40002690, 2025).
thyroid carcinoma (1 paper, 2025). "Importantly, the highest correlation was detected between the MIDN expression and infiltration of neutrophils in thyroid carcinoma (THCA)." (PMID 40002690, 2025).
uterine carcinosarcoma (1 paper, 2025). A usually aggressive malignant neoplasm arising from the uterine corpus and less often the cervix. "The MIDN level was positively linked with the TMB of uterine carcinosarcoma (UCS) and negatively linked with the TMB of CHOL." (PMID 40002690, 2025).